SOD2 (superoxide dismutase 2)
Diseases named in the same sentence as SOD2 in open-access papers (continued):
Sharing a sentence is not in itself a finding about the gene and the disease.
lung carcinoma (58 papers, 2004 to 2025). "Serum SOD2 has been shown to be positively associated with all-cause mortality in lung cancer patients and resistance to EGFR-tyrosine kinase inhibitors in NSCLC." (PMID 38082189, 2024). "CSE induced low expressions of Sirt3 and SOD2 (P<0.01), and Sirt3/SOD2 was associated with poor prognosis in lung cancer patients (P<0.05)." (PMID 37183639, 2023). "Most importantly, our analysis indicated that the serum SOD1 and SOD2 concentrations are good prognostic parameters of all-cause mortality in lung cancer." (PMID 34832849, 2021). "Increased serum SOD1 concentration per 1 pg/mL and SOD2 per 1 ng/mL were significantly associated with a 0.4 and 19% higher HR, respectively, for all-cause mortality in lung cancer patients." (PMID 34832849, 2021). "The results of a meta-analysis strongly suggest that the rs4880 polymorphism in SOD2 is significantly associated with the occurrence of lung cancer." (PMID 32648197, 2021). "The serum SOD1 concentration appears to be better than the SOD2 concentration for the prediction of all-cause mortality in lung cancer, as demonstrated by our Kaplan–Meier overall survival estimates." (PMID 34832849, 2021). "Serum SOD1 and SOD2 concentrations were shown to positively affect all-cause mortality in lung cancer patients, but SOD1 seems to be a better predictor than SOD2." (PMID 34832849, 2021). "The models confirmed that elevated serum SOD1 and SOD2 concentrations significantly increased the HR of all-cause mortality in lung cancer patients." (PMID 34832849, 2021). "Four studies described that wild-type TT genotype of SOD2 rs4880 T/C polymorphism was associated with an increased lung cancer risk in Caucasian population, while two on Asian population did not identify similar association even after stratification analysis." (PMID 28272301, 2017). "Additionally, one meta-analysis strongly suggests that changes in SOD2 activity associated with C47T polymorphism have an impact on the risk of lung cancer development." (PMID 34832849, 2021). "The results of 2 meta-analyses of rs4880 in SOD2 suggest its association with lung cancer risk." (PMID 30640897, 2019). "During lung cancer chemotherapy, SOD2 overexpression increases resistance to the tyrosine kinase inhibitor anlotinib, used as a third line of treatment for patients with advanced NSCLC." (PMID 37108069, 2023). "Exogenous C8-ceramide induces ROS and apoptosis in lung cancer H1299 cells by upregulating mitochondrion-located SOD2." (PMID 33807834, 2021). "All-cause mortality in lung cancer was positively associated with serum SOD1 and SOD2 concentrations." (PMID 34832849, 2021). "The median serum SOD1 and SOD2 concentrations were significantly higher in lung cancer patients compared to control subjects (218.9 vs. 141.0 pg/mL, and 1.30 vs. 0.78 ng/mL, respectively)." (PMID 34832849, 2021). "In conclusion, higher SOD1 and SOD2 concentrations were shown to positively affect the risk of all-cause mortality in lung cancer patients, but the serum SOD1 concentration appears to be a better predictor than the serum SOD2 concentration." (PMID 34832849, 2021). "Conversely, in another study, the SOD2 activity determined in the leukocyte cells of lung cancer patients was lower than that of the control group." (PMID 34832849, 2021). "In the present study, overexpression or knockdown SOD2 in lung cancer cells showed that SOD2 promotes cancer cell invasion." (PMID 30755594, 2019). "Recently, it was demonstrated that PKC-ERK1/2 signal transduction upregulates mitochondrial SOD2 expression in response to glucose starvation in lung carcinoma cells." (PMID 29478325, 2019). "Nonetheless, they are counter to what shown in mice with lung cancer-induced cachexia in which protein levels of SOD2 were significantly decreased in their respiratory and limb muscles, while levels of SOD1 were not modified by cachexia in the same animals." (PMID 29255650, 2017).
lung carcinoma (continued). "A study concluded that serum SOD1 concentration was a better predictor than serum SOD2 concentration, however both SOD1 and SOD2 concentrations have been demonstrated to positively impact the risk of all-cause mortality in patients with lung cancer." (PMID 40867576, 2025). "Our findings confirm the first study’s hypothesis to a good extent: SOD1 and SOD2 concentrations were higher in lung cancer patients than in the control group." (PMID 34832849, 2021). "However, serum SOD1 and SOD2 concentrations significantly predicted mortality in lung cancer patients." (PMID 34832849, 2021). "Consistently, the decrease of SOD1 and SOD2 ratio was also observed in H1299 cells following C8-ceramide treatment, suggesting that the anti-lung cancer effects of C8-ceramide may be closely correlated with the mechanism of SOD1 to SOD2 switch." (PMID 30279365, 2018). "Additionally, levels of SOD2 were also shown to be reduced in the diaphragm of mice with lung cancer-induced cachexia that were studied for one month." (PMID 29255650, 2017). "Recently, NRF2 has been shown to act on the promoter of the superoxide dismutase 2 (SOD2) gene by ChIP-qPCR analysis and to increase its mRNA and protein expression in human lung cancer cells." (PMID 40430023, 2025). "For lung cancer, the knock-down of LncRNA-XIST inhibits tumour progression by triggering miR-335/SOD2/ROS signal pathway mediated pyroptotic cell death." (PMID 36039017, 2022). "According to multiple Cox regression models predicting lung cancer mortality, only serum concentrations of SOD1 and SOD2 and advanced clinical (III–IV) stages of disease remained statistically significant." (PMID 34832849, 2021). "Activation of NFE2L2 negatively regulates ferroptosis in various cells (including lung cancer cells) by upregulating various target genes, e.g. heme oxygenase 1 (HMOX1), SLC7A11, GPX4, and superoxide dismutase 2 (SOD2)." (PMID 34742351, 2021). "Serum total SOD activity and SOD1, SOD2, albumin, CRP, and ceruloplasmin concentrations were determined in lung cancer patients (n = 190) and control subjects (n = 52)." (PMID 34832849, 2021). "A survey of SOD isoform concentrations in the sera of lung cancer patients revealed significant alterations in both SOD1 and SOD2 levels in comparison with control subjects." (PMID 34832849, 2021). "The rs4880 in SOD2 and rs1050450 in GPX1 were previously tested in lung cancer patients, however the results were inconclusive." (PMID 30640897, 2019). "Serum total SOD activity and SOD2 concentration did not significantly distinguish lung cancer patients from control subjects." (PMID 34832849, 2021). "Moreover, most previous studies concerning SOD in lung cancer focused only on one or two parameters: total SOD, or SOD1 and SOD2 concentrations." (PMID 34832849, 2021). "Moreover, in this study, the cutoff values of serum SOD1 and SOD2 concentrations significantly differentiated lung cancer patients from the control group (SOD1), and predicted mortality in the studied group of lung cancer patients (SOD1 and SOD2)." (PMID 34832849, 2021). "In the present investigation, levels of the antioxidant enzyme SOD1, but not those of SOD2 or catalase, were significantly greater in the tumors of the lung cancer-bearing mice treated with the monoclonal antibodies." (PMID 31487876, 2019). "However, no research on disturbances in serum SOD1 and SOD2 concentrations has been performed in lung cancer patients." (PMID 34832849, 2021). "Additionally, neither serum total SOD activity nor serum SOD1 and SOD2 concentrations were found to be useful indicators in determining clinical stage IV lung cancer." (PMID 34832849, 2021).
gastric cancer (52 papers, 2005 to 2025). A primary or metastatic malignant neoplasm involving the stomach. "LncRNA GClnc1 (gastric cancer-associated lncRNA 1), which has been shown to promote gastric cancer, specifies the pattern of histone modification on superoxide dismutase 2 through a modular scaffold of WDR5 and KAT2A complexes." (PMID 32575858, 2020). "In a previous study, the Ala variant of SOD2 increased the risk of gastric cancer by altering the activity or content of SOD2 to lower its ability to detoxify ROS." (PMID 24348785, 2014). "Another study demonstrated that gastric cancer-associated lncRNA1 (GClnc1) could act as a scaffold lncRNA linking WDR5 and KAT2A, triggering proliferation, invasion and metastasis by activating SOD2 in GC." (PMID 36419649, 2022). "Cases with higher SOD2 activity of the tumor were associated with worse overall survival in renal cell cancer patients as well as occurrence of distant metastasis and reduced survival in salivary adenoid cystic cancer and gastric cancer." (PMID 34200699, 2021). "It has been found that SOD2 is highly expressed in a variety of tumors such as oral squamous cell carcinoma cells and gastric cancer cells, and plays an important role in several biological aspects of tumors." (PMID 39871949, 2024). "Overexpression of SOD2 (P04179) has also been shown to increase doxorubicin resistance in gastric carcinoma cells." (PMID 33750814, 2021). "GClnc1 coordinates WDR5 and KAT2A localization and specifies the histone modification pattern of the target gene SOD2, indicating that GClnc1 is functionally an oncogenic factor in gastric cancer." (PMID 29721215, 2018). "An involvement of MDF in gastric cancer was suggested by SOD-2 overexpression and by the recent report that found H. pylori-induced mtDNA mutations and a decrease of mtDNA content." (PMID 24876913, 2014). "Several studies have reported that the overexpression of SOD2 is relevant to poor clinical outcome in gastric cancer, and SOD2 may promote intestinal inflammation and tumorigenesis." (PMID 35493741, 2022). "The expression of SOD2 that protects the host against reactive oxygen and reactive nitrogen species, but is also involved in metabolic reprogramming in gastric cancer was also increased (FC = 14)." (PMID 35531332, 2022). "Increased SPARC expression is linked to advanced gastric cancer, although the expression of SOD2 (Mn-SOD; manganese superoxide dismutase) was significantly enhanced in cancer tissues compared with normal mucosa, and the Mn-SOD ratio was proposed as an independent prognostic parameter." (PMID 18827816, 2008). "A study showed that SOD2 was elevated in gastric cancer (GC)." (PMID 40867576, 2025). "The expression of SOD2 (Mn-SOD), superoxide anion scavenger, is elevated, but the expression of SOD1 (copper/zincSOD) is decreased while comparing gastric cancer tissues with their matching normal mucosa." (PMID 37143652, 2023). "The lncRNA GClnc1 is up-regulated in human gastric cancer tissues, and WDR5 binds GClnc1 to regulate the transcription of oncogenes, such as SOD2, and consequently induces gastric cancer cell proliferation, invasion and metastasis." (PMID 30488017, 2018). "Three of these are known to be involved in gastric cancer: MMP7, SPARC, and SOD2, and the other four have no such reported associations (INHBA, IGFBP7, NEK6, and LUM)." (PMID 18827816, 2008).
colorectal cancer (44 papers, 1998 to 2025). A primary or metastatic malignant neoplasm that affects the colon or rectum. "Mutations in the SOD2 gene promoter have been reported to impact the AP2 binding pattern in colorectal cancer cells, resulting in loss of SOD2 expression." (PMID 35164076, 2022). "Here, we show that the inhibition of the superoxide dismutase 2 (SOD2) sensitizes different cancer entities, including leukemia and colorectal cancer cells, to amino acid starvation independently of known SOD2-associated pathways, including reactive oxygen species (ROS) signaling." (PMID 40131931, 2025). "Conversely, the suspected dysplasia was characterized by the expression of CXCL2/3 (inflammatory markers), LCN2 (a secretory protein potentially acting as a tumor suppressor in colorectal cancer), and SOD2 and NCOA7 (stress response genes)." (PMID 40667282, 2025). "Zhao and co-workers showed that kaempferol at the concentration of 10 μg/mL increased the SOD2 activity in the human colorectal cancer cell line (Caco-2)." (PMID 35056649, 2022). "It is of therapeutic relevance that the hsa-miR-324-inducing 4-AAQB inhibits the SOD2-mediated motility, invasiveness, and clonogenicity of colorectal cancer SP cells." (PMID 30103475, 2018). "SIRT3 overexpression in colorectal cancer cells also decreased FoxO3a acetylation and increased FoxO3a binding to the SOD2 promoter, whereas expression of a SIRT3 catalytic mutant did not affect the DNA binding ability of FoxO3a." (PMID 29099803, 2017). "Conversely, mutations found in the SOD2 gene promoter influence the binding pattern of AP-2 in colorectal cancer cells and downregulate SOD2 expression." (PMID 29099803, 2017). "We investigated the effects of radiation-induced overexpression of SOD2 both in human colorectal cancer cell HT-29 and in normal colorectal cell line CCD 841 CoN." (PMID 27999194, 2017). "Both in vitro and in vivo studies have shown that overexpression of SOD2 combined with radiotherapy can effectively increase the radiation sensitivity of colorectal cancer cells while having radioprotective effects on colon epithelial cells and skin tissue." (PMID 27999194, 2017). "Positive staining of SOD2 is seen in the cytoplasm of colorectal cancer cells, in which brown-yellow particles are dispersed." (PMID 27999194, 2017). "Our present study showed that radiation-induced SOD2 gene expression enhances the radiosensitivity of colorectal cancer cells while demonstrating radioprotective effects on colon epithelial cells and skin tissue." (PMID 27999194, 2017). "SOD2 expression was found to be down in breast, esophageal, and pancreatic cancer, but up in ovarian, gastric and colorectal cancer." (PMID 27221200, 2016). "Thus radiation-induced SOD2 overexpression via the chimeric C9BC promoter increased the radiosensitivity of HT-29 human colorectal cancer cells and concurrently protected normal CCD 841 CoN colorectal cells from radiation damage." (PMID 27999194, 2017). "The findings showed that SOD2 overexpression could promote cell apoptosis in colorectal cancer while inhibiting cell apoptosis in normal colon epithelial cell." (PMID 27999194, 2017). "Consequently, it can be assumed that the tested compounds have a higher affinity for SOD2 than SOD1, and thus, with prolonged exposition, a lower amount of the protein can be expected, which translates into reduced antioxidant capacity of colorectal cancer cells and associated cell death." (PMID 39195258, 2024). "SOD2 contributes to the chemical resistance of colorectal cancer, and according to research, MAPK8 can promote the progression of colorectal cancer." (PMID 36299603, 2022). "This study investigated whether radiation-induced overexpression of superoxide dismutase 2 (SOD2) exerts radio-sensitizing effects on tumor cells while having radio-protective effects on normal cells during radio-activated gene therapy for human colorectal cancer." (PMID 27999194, 2017).
colorectal cancer (continued). "Finally, future studies should incorporate the distinct roles of different SOD isoforms (SOD1, SOD2, and SOD3) in colorectal cancer prognosis, as their specific contributions may influence biomarker development and clinical applications." (PMID 41479776, 2025).
atherosclerosis (42 papers, 2007 to 2025). A disease characterized by the build-up of fatty material and calcium deposition in the arterial wall resulting in partial or complete occlusion of the arterial lumen. "For instance, these processes were observed in atherosclerosis models, such as apoe −/− atherosclerotic mice deficient for superoxide dismutase-2 (SOD-2)." (PMID 34445694, 2021). "In the previous study, SOD2 deficiency (SOD2+/−) leads to mitochondrial dysfunction, increased mitochondrial DNA damage and accelerated atherosclerosis in ApoE-KO mice." (PMID 26633327, 2015). "Knowing that SOD2 is a manganese-containing enzyme, we expected the result that the manganese content correlated with the degree of advancement of atherosclerosis, especially since there are publications that describe how the increase in Mn concentration in blood is associated with atherosclerosis." (PMID 34202347, 2021). "To validate the potential role of the SIRT3/SOD2 pathway in Micu1-regulated atherosclerosis, we analyzed SIRT3 expression and levels of acetylated SOD2 in aortic root sections of hypercholesterolemic Micu1ECKO and Micu1fl/fl mice." (PMID 40166941, 2025). "In this study, we demonstrated the role of MICU1 in regulating SIRT3/SOD2 activity in the context of vascular inflammation and atherosclerosis." (PMID 40166941, 2025). "Idebenone, which is a compound similar to co-enzyme Q10, also increases SIRT3 activity and further activates SOD2, which suppresses ROS to ameliorate atherosclerosis in ApoE−/− mice." (PMID 35453391, 2022). "In an atherosclerosis mouse model established by feeding a HFD, miR-146a derived from oxidized low-density lipoprotein treated THP-1 cells exosomes enhanced the atherosclerotic plaque area and led to atherosclerosis deterioration via targeting SOD2." (PMID 35884901, 2022). "A tendency was observed that the more advanced the atherosclerosis, the more SOD2 antigen was present in the artery wall." (PMID 34202347, 2021). "The disease process in atherosclerosis prone mice accentuated when mitochondrial antioxidant capacity was weakened by lower superoxide dismutase 2 activity." (PMID 28704533, 2017). "SOD2 can regulate mitochondrial ROS and control endothelial dysfunction and apoptosis, leading to the development of atherosclerosis." (PMID 27830142, 2016). "The observed positive correlation between atherosclerosis progression and high levels of LDL-cholesterol in CHD patients was associated with the SOD2-Val/Val genotype." (PMID 27067415, 2016). "Further studies show that blueberry supplementation attenuated atherosclerosis by upregulating expression of the antioxidant enzymes SOD1, SOD2, GSR, and thioredoxin reductase- (TR-) 1 in ApoE deficient mouse models of atherosclerosis." (PMID 23691264, 2013). "Idebenone, a short-chain benzoquinone, similar in structure to coenzyme Q10, protects against atherosclerosis in apolipoprotein E-deficient mice by clearing oxygen free radicals and inhibiting NLRP3 activation via the SIRT3/superoxide dismutase 2 (SOD2)/mitochondrial ROS pathway." (PMID 39372420, 2024). "ApoE−/−/SOD2+/− mice showed increased atherosclerosis and plaque vulnerability." (PMID 35883899, 2022). "In addition to preventing ROS production and DNA damage in mitochondria, SOD2 regulates endothelial myocytes’ proliferation and apoptosis, inhibiting the development of atherosclerosis." (PMID 34202347, 2021). "Thus, we hypothesize that MICU1 regulates vascular inflammation and atherosclerosis potentially through the SIRT3/SOD2/mROS pathway." (PMID 40166941, 2025). "Aberrant methylation of several genes, including SOD2, FGF2, ABCA1, COX2, and SMAD7, have been identified as key progressor of T2DM-related atherosclerosis." (PMID 38323108, 2024). "The results of RNA sequencing analysis showed that many antioxidant genes were enriched in Fluid shear stress and atherosclerosis pathway, including MGST1, GSTM3, GSTA1, SOD2 and GSTA4." (PMID 36978937, 2023).